ZNF660 (zinc finger protein 660)
Description:
May be involved in transcriptional regulation.
Synonyms: FLJ36870
Tractability: PROTAC: ubiquitination databases record sites on it.
Gene: Protein-coding gene on chromosome 3 (44,578,223 to 44,599,694, forward strand). Ensembl gene ENSG00000144792.
Subcellular location: Nucleus
Subcellular location (Human Protein Atlas): Cytosol; Nucleoli fibrillar center
Pathways (Reactome):
Gene expression (Transcription): Generic Transcription Pathway
Gene Ontology:
Molecular function: protein binding; sequence-specific double-stranded DNA binding; DNA-binding transcription factor activity; RNA polymerase II cis-regulatory region sequence-specific DNA binding
Biological process: regulation of transcription by RNA polymerase II
Cellular component: nucleus
Genetic constraint (gnomAD): Loss-of-function variants: 24 observed, 25.88 expected, observed/expected ratio (o/e) 0.93, 90% interval 0.67 to 1.3. The upper end of that interval is the gene's LOEUF score, 1.3, which puts it in group 5 of 6, group 1 being the genes least tolerant of losing a copy. Missense variants: 373 observed, 419.14 expected, observed/expected ratio (o/e) 0.89, 90% interval 0.82 to 0.97. Synonymous variants: 117 observed, 139.67 expected, observed/expected ratio (o/e) 0.84, 90% interval 0.72 to 0.98.
Homologues: Orthologues: rabbit ZNF660 (95% identical), pig ZNF660 (93% identical), guinea pig ZNF660 (92% identical), rat Znf660 (87% identical). Paralogues in human: ZNF79 (53% identical), ZNF304 (51% identical), ZNF551 (50% identical), ZSCAN2 (50% identical), ZSCAN20 (50% identical), ZNF480 (49% identical), ZNF583 (49% identical), ZNF792 (48% identical), ZNF587B (48% identical), ZNF256 (48% identical), ZNF549 (46% identical), ZNF570 (45% identical), and 26 more.
Diseases named in the same sentence as ZNF660 in open-access papers:
ZNF660 is named in the same sentence as 5 diseases in open-access papers, as found by Europe PMC text mining. Sharing a sentence is not in itself a finding about the gene and the disease. The quoted sentences say what the papers report.
prostate carcinoma (2 papers, 2018 to 2021). A carcinoma that arises from epithelial cells of the prostate gland. "We report significant aberrant ST6GALNAC3 and ZNF660 promoter hypermethylation in PC in multiple large patient cohorts, as well as a significant association of ZNF660 hypermethylation with high risk of BCR and reduced overall survival (OS) and prostate cancer‐specific survival (CSS)." (PMID 29465788, 2018). "In the same study, using ddPCR, promoter methylation of these two genes (ST6GALNAC3 and ZNF660) and additionally CCDC181 and HAPLN3 was evaluated in ctDNA of 27 patients with prostate cancer and 10 patients with benign prostate hyperplasia using MS‐ddPCR." (PMID 33942482, 2021). "Promoter methylation of two genes, namely ST6GALNAC3 and ZNF660, after being evaluated in 705 prostate cancer tissues and 110 nonmalignant tissue samples, was reported to be cancer‐specific with an area under curve in ROC curves of 0.917–0.995 and 0.846–0.903." (PMID 33942482, 2021).
cancer (2 papers, 2018 to 2021). A tumor composed of atypical neoplastic, often pleomorphic cells that invade other tissues. "In conclusion, we here conducted a large‐scale study showing highly cancer‐specific ST6GALNAC3 and ZNF660 hypermethylation, demonstrating promising diagnostic potential." (PMID 29465788, 2018). "In ROC curve analysis, both ST6GALNAC3 and ZNF660 hypermethylation was highly cancer‐specific with AUCs ranging from 0.917 to 0.995 (ST6GALNAC3) and from 0.894 to 0.903 (ZNF660) in the three patient sets." (PMID 29465788, 2018). "We here found cancer‐specific promoter hypermethylation of ST6GALNAC3 and ZNF660 in PC compared to benign prostate tissue samples in four different patient sets." (PMID 29465788, 2018).
tumor (1 paper, 2018). "Next, to assess whether ST6GALNAC3 and ZNF660 promoter methylation levels in PC tissue samples could be associated with tumor aggressiveness, we evaluated possible associations between promoter methylation levels and standard clinicopathological prognostic variables." (PMID 29465788, 2018). "Moreover, as proof of principle, we successfully detected highly PC‐specific hypermethylated circulating tumor DNA (ctDNA) for ST6GALNAC3,ZNF660,HAPLN3, and CCDC181 in liquid biopsies (serum) from 27 patients with PC vs. 10 patients with BPH, using droplet digital methylation‐specific PCR analysis." (PMID 29465788, 2018).
ZNF660 also shares sentences with these, for which no sentence is quoted: benign prostatic hyperplasia (1 paper); prostatic intraepithelial neoplasia (1).